BRAF (B-Raf proto-oncogene, serine/threonine kinase)
Diseases named in the same sentence as BRAF in open-access papers (continued):
Sharing a sentence is not in itself a finding about the gene and the disease.
melanoma (continued). "By integrating our functional genomic and (phospho)proteomic data, we identified ROCK1 as a potential drug target for BRAF mutant melanoma." (PMID 25538140, 2014). "MEL9, the adrenal gland metastasis that was hypermutated, harbored mutations in both BRAF (H574L) and NRAS (Q61R); these two mutations were found to be present in the same variant allele frequency cluster (see Subclonal architecture in melanoma below)." (PMID 25393105, 2014). "Clinically validated driver genes include the mutant oncoproteins BRAF (∼50% of melanomas), c-Kit (∼15%) and NRAS (∼20%)." (PMID 25538140, 2014). "In melanoma cells harboring the NRAS mutation, the mutated NRAS protein needs CRAF to activate the MEK/ERK pathway, and the BRAF protein is phosphorylated by ERK on S151 near the RAS binding domain, which results in the inhibition of the NRAS/BRAF interaction." (PMID 25422890, 2014). "Treatment of BRAFV600E-mutant melanoma by small molecule inhibitors that target BRAF or MEK kinases is increasingly used in clinical practice and significantly improve patient outcome." (PMID 25526463, 2014). "For example, BRAF inhibitors can be very effective in melanoma patients with BRAF mutant tumors, but have been much less effective in BRAF mutant colorectal cancer and in Ras mutant tumors." (PMID 25520658, 2014). "We show that RAS mutant melanoma cells are more resistant to drugs affecting DNA synthesis than BRAF mutant cells." (PMID 24941944, 2014). "A member of this family, BCL2A1, was shown to be amplified in 30% of melanoma and contribute to resistance to BRAF inhibition (see section “Intrinsic Resistance to BRAF and MEK Inhibitors”)." (PMID 24743024, 2014). "In summary, these two recent reports provide important new insights into some of the complexities associated with targeting the BRAF-MEK-ERK signaling pathway in BRAF mutant melanoma." (PMID 25031620, 2014). "Our results warrant exploration of combinations of BRAF/ROCK inhibition or ERK/ROCK inhibition in further studies for the treatment of BRAF mutant melanoma." (PMID 25538140, 2014). "The combination of the MEK inhibitor, trametinib, and BRAF inhibitor, dabrafenib, was approved for the treatment of melanoma in 2014." (PMID 25520658, 2014). "We showed that TRIM16 protein expression by IHC was significantly increased in patient melanoma tissues during early treatment with BRAF inhibitors (p=0.0018, two sided t-test, 95% confidence intervals 0.4 to 1.3) and reduced at relapse." (PMID 25333256, 2014). "Previous studies have investigated the ability of metabolic modulators to improve the therapeutic effect of BRAF inhibitors for treatment of melanoma." (PMID 25182332, 2014). "The BRAF inhibitor, vemurafenib, increased TRIM16 protein levels in melanoma cells in vitro, and induced growth arrest in BRAF-mutant melanoma cells in a TRIM16-dependent manner." (PMID 25333256, 2014). "Because of this overlap, we were able to stringently select for factors that are useful as targets in combination with inhibition of the BRAF/MAPK pathway in melanoma." (PMID 25538140, 2014). "Combining vemurafenib and SCH722984 in BRAF mutant melanoma was synergistic in a majority of cell lines and significantly delayed the onset of acquired resistance in long term in vitro assays." (PMID 25142146, 2014). "Activated BRAF/MAPK signaling was shown to be essential in the development of immune evasion in melanoma." (PMID 24743024, 2014). "As a model system, we used a panel of BRAF mutant human melanoma cell lines sensitive to PLX4720 treatment." (PMID 25538140, 2014). "This mutation accounts for >90% of all BRAF mutations detected thus far in cutaneous melanoma, leading to ERK activation and a subsequent proliferation and survival advantage in melanoma cells." (PMID 25120707, 2014). "Transcription factor FOXD3 was shown to be upregulated when mutant BRAF is inhibited in melanoma cell lines." (PMID 24743024, 2014).
melanoma (continued). "Amplification of the family member, BCL2A1 in 30% of melanoma, was shown to contribute to resistance to BRAF inhibition." (PMID 24743024, 2014). "Since many resistance mechanisms are MAPK pathway dependent, clinical trials in which melanoma patients are treated simultaneously with BRAF and MEK inhibitor are ongoing." (PMID 25538140, 2014). "Mutations that constitutively activate the serine/threonine kinase, BRAF (predominantely the oncogenic BRAFV600E) have been reported in 60–70% of malignant melanomas." (PMID 24466036, 2014). "Next, we immunostained the additional 104 tumor specimens with VE1, and also included 22 in situ melanomas, hence, together with previously stained 45 specimens we obtained data on BRAF-mutant expression of 171 tissues." (PMID 25526463, 2014). "CH5126766 suppressed not only BRAF, but also CRAF kinase activity, and we conclude that CH5126766 is an attractive RAF/MEK inhibitor in RAS-mutated malignant tumor cells including melanoma." (PMID 25422890, 2014). "SCH772984 was able to suppress growth of melanoma cells engineered to contain amplified BRAFV600E and even growth of melanoma lines selected for double resistance to BRAF and MEK inhibition." (PMID 24743024, 2014). "Mutations of the two oncogenes (BRAF and NRAS) have a well established and powerful predictive role as validated targets in recently developed molecular targeted therapy for melanoma." (PMID 24959217, 2014). "Translating this to a preclinical setting, a ROCK inhibitor showed augmented melanoma cell death upon BRAF or ERK inhibition in vitro." (PMID 25538140, 2014). "To evaluate the possible therapeutic application of TRIM16 expression patterns on the treatment of melanoma, we investigated the effect of the BRAF inhibitor, vemurafenib, on TRIM16 expression levels." (PMID 25333256, 2014). "This process was performed using a BRAFV600E/PTEN–/–syngeneic subcutaneous mouse model, which showed an increase in intratumoral CD8 T cells after BRAF inhibitor initiation, similar to melanoma patients." (PMID 25610709, 2014). "In BRAF mutant melanoma cells, Usp5 activity was suppressed by BRAF inhibitor (vemurafenib) in sensitive but not in acquired or intrinsically resistant cells." (PMID 24980819, 2014). "In our study, of the melanoma cell lines tested for the effects of MIF inhibition, three express wildtype BRAF (Me1007, MelRM and MelFH) while the others bear the BRAF V600E mutation (MelCV, MelRMu and MM200)." (PMID 25168062, 2014). "The distribution of BRAF and NRAS mutations in this cohort was similar to that in previously reported studies (particularly consistent with stage IV melanoma) with mutually exclusive BRAF-mutants found in 62% and NRAS-mutants in 17% of cases." (PMID 24959217, 2014). "One of the key oncogenic pathways most frequently altered in melanoma is the RAS/BRAF/MEK pathway, thus providing potential promising therapeutic targets." (PMID 24238212, 2013). "Recurrent rearrangements of the RAF kinases, RAF1 and BRAF, were recently reported in a small fraction of prostate cancers, gastric cancers, and melanomas." (PMID 23637631, 2013). "Based on these observations, we propose that the mitochondrial oxidative signature of resistant melanoma constitutes a novel opportunity to overcome resistance to BRAF inhibition." (PMID 24161908, 2013). "Dabrafenib was also evaluated in a multicenter, open-label, phase 2 trial, in patients with Val600Glu or Val600Lys BRAF-mutant melanoma metastatic to the brain." (PMID 23340652, 2013). "Both our IHC and molecular study demonstrated homogeneity between primary and metastatic sites for BRAF status in melanoma." (PMID 23976959, 2013). "Targeting oncogenic BRAF with PLX4720 or PLX4032 resulted in inhibition of growth and invasion of three-dimensional melanoma spheroids into a collagen matrix and caused tumor regression of melanoma xenografts without evidence of toxicity." (PMID 27429258, 2013).
melanoma (continued). "We further analyzed the ex-vivo inhibitory effects of the BRAF inhibitor, vemurafenib, and the multi-targeted tyrosine kinase inhibitor, sunitinib, in the same set of melanoma samples." (PMID 24023633, 2013). "In this study, we have characterized the BRAF and NRAS mutation status of a series of melanoma cell lines developed from New Zealand patients with metastatic melanoma." (PMID 23658559, 2013). "AMPK activators phenformin and AICAR were shown to inhibit the cell growth of both BRAF-mutant or NRAS-mutant melanoma cell, due to cell-cycle arrest in either the G0/G1 or the S phase, associated with an increased expression of the p21 cell-cycle inhibitor." (PMID 23875169, 2013). "It was recently reported that STAT3 inhibitors also restored drug sensitivity of melanoma cells which had acquired resistance to BRAF inhibitors." (PMID 23755373, 2013). "Since there is a strong clinical interest in combined immunotherapy and BRAF/MEK inhibition in melanoma, the direct impact of MAPK pathway inhibition on immune cells is of great interest." (PMID 24194739, 2013). "More recently, HGF was reported to induce resistance to ALK selective inhibitors in EML4-ALK lung cancer and BRAF inhibitors in BRAF mutant melanoma." (PMID 23690929, 2013). "Noteworthy, PPP6C mutations were more frequent in melanomas that were mutated for both BRAF and NRAS, while RAC1 mutations were more frequent in melanomas that were wild-type for both BRAF and NRAS." (PMID 24416617, 2013). "A common mutation of BRAF (V600E), a molecule in MAPK signal pathway, was identified by systematic DNA sequencing of signaling molecules in human melanoma cells." (PMID 23755373, 2013). "Oncogenic RAS or BRAF alone appears relatively poor in inducing melanoma transformation unless they are combined with other genetic alterations." (PMID 24416617, 2013). "To obtain key parameters for our model, we have studied the dynamics of 68 index lesions in 20 melanoma patients receiving the BRAF inhibitor vemurafenib." (PMID 23805382, 2013). "Genomic DNA from 513 consecutively-collected patients with advanced melanoma (AJCC stages III and IV) was screened for somatic mutations in the exon 15 of BRAF gene." (PMID 23987572, 2013). "We have evaluated the role of mutant BRAF (V600E) in human melanoma cells by using mutant BRAF (V600E)-specific lentiviral shRNAs, and found that BRAF mutation was involved in enhanced cell proliferation and invasion." (PMID 23755373, 2013). "Using molecular techniques, several studies have reported intra-tumor heterogeneity for BRAF status in melanoma." (PMID 23976959, 2013). "Reports also demonstrate that PRMT5 regulates ERK signal transduction amplitude in BRAF wild type melanoma cell lines." (PMID 24098663, 2013). "Significantly differentially affected kinase substrates (P<0.05) between BRAF(V600E) and BRAF wild-type melanoma in lysates from cell lines and tumor tissue." (PMID 24023633, 2013). "Malignant melanoma is a devastating malignancy for which few effective targeted treatments (e.g., BRAF inhibitors) are available." (PMID 23825798, 2013). "There has been much development in the area of tumour-stroma interactions dictating treatment resistance, with much recent interest in how hepatocyte growth factor (HGF) can mediate BRAF-inhibitor resistance in melanoma." (PMID 23762429, 2013). "In one patient, clinical history supported the emergence of a second melanoma with a different BRAF status." (PMID 23976959, 2013). "Mutations have been detected in BRAF, NRAS and c-KIT which lead to activation of the RAS/RAF/MEK/ERK pathway and dysregulation of melanoma cell proliferation." (PMID 24276125, 2013). "Melanoma specimens were tested for BRAF V600 mutations at two laboratories with the: cobas BRAF Mutation Test; ABI BRAF test; and bidirectional direct sequencing." (PMID 23326492, 2013). "High numbers of BRAF and NRAS mutations were identified with frequencies varying according to melanoma subtype." (PMID 23694694, 2013).
melanoma (continued). "In the current study, we examined mitochondrial metabolism and ROS production in several melanoma cell lines that exhibit acquired resistance to the BRAF inhibitor, vemurafenib." (PMID 24161908, 2013). "Recently, we found that activation of Wnt/β-catenin signaling can enhance apoptosis in melanoma cells treated with targeted BRAF inhibitors." (PMID 23869245, 2013). "Although BRAF mutations can be identified from the very earliest stages of melanoma onset, targeted BRAF inhibitor therapies are presently validated for use in advanced stage IV melanomas." (PMID 24381933, 2013). "BRAF mutations that constitutively activate MAPK signalling and bypass the need for upstream stimuli occur with high prevalence in melanoma, colorectal carcinoma, ovarian cancer, papillary thyroid carcinoma, and cholangiocarcinoma." (PMID 23844038, 2013). "BRAF mutations affect a large variety of cancers; however, response rates to Braf inhibitors differ significantly, ranging from 80% in melanoma to less than 10% in BRAF mutant CRC." (PMID 23845441, 2013). "Nevertheless, Brn3a was able to reduce BRAF-induced DNA damage in normal cells and DNA damage has also been observed in melanoma cells upon Brn3a inhibition." (PMID 23666755, 2013). "One patient developed a second primary melanoma after more than 4 months of therapy (BRAF and RAS wild type)." (PMID 23516541, 2013). "On the contrary, differentiated melanoma cells were exquisitely sensitive to MEK inhibition regardless BRAF status, undergoing massive apoptosis upon treatment." (PMID 24238212, 2013). "Eligible patients had histologically confirmed BRAF-mutant melanoma and at least one asymptomatic brain metastasis." (PMID 24455677, 2013). "The authors concluded that dabrafenib was safe in patients with solid tumors, and was an active inhibitor of V600-mutant BRAF with responses noted in patients with melanoma, brain metastases, and other solid tumors." (PMID 23617957, 2013). "Overall, this study highlights the efficacy and safety of dabrafenib in patients with treated or untreated (and progressed) BM from BRAF-mutant melanoma." (PMID 24455677, 2013). "In melanoma cell lines, MEK and BRAF inhibition leads to increased expression of melanoma differentiation antigens (MDAs) such as gp100, MART-1, and tyrosinase on the mRNA and protein levels." (PMID 24194739, 2013). "This is believed to explain why only a minority of benign melanocytic nevi frequently expressing BRAF(V600E) finally progress to malignant melanoma." (PMID 23887651, 2013). "The discovery of constitutively activating mutations in the BRAF and KIT genes in subsets of melanoma has expanded treatment options to include specific molecularly targeted kinase inhibitors such as vemurafinib and imatinib." (PMID 24220097, 2013). "Recently, two BRAF inhibitors that preferentially inhibit mutant BRAF in cancer cells have been developed, and their administration resulted in regression of melanoma in clinical trials." (PMID 23755373, 2013). "Irrespective of the mechanisms, we have shown that pre-incubation with inhibitors of mitochondrial function renders melanoma cells more sensitive to BRAF inhibitors." (PMID 24161908, 2013). "Locally invasive melanoma and distant metastatic phenotypes were reported in the HGF/SF-transgene Ink4aARF−/−, Tyr-N-RasQ61K INK4A−/− and in the BRaf V600E Pten−/− mouse models of melanoma." (PMID 27429258, 2013). "In our study, kinase substrates encoding for EGFR and PDGFRβ were found to be significantly differentially affected by ex-vivo vemurafenib in melanoma tumors harboring BRAF(V600E) and BRAF wild-type." (PMID 24023633, 2013). "It is critical for the field of melanoma therapeutics, to enhance the longevity of the successful responses obtained with BRAF inhibitors." (PMID 23515890, 2013). "In vivo, vemurafenib suppresses ERK signaling and hence tumor cell proliferation and survival in mutant BRAF melanoma, but lacks activity in wild-type BRAF melanoma cell lines." (PMID 24499550, 2013).
melanoma (continued). "Vemurafenib is a potent inhibitor of V600 mutant BRAF with significant impact on progression-free and overall survival in advanced melanoma." (PMID 23516541, 2013). "Activating mutations in the serine/threonine kinases BRAF, and NRAS were identified in 66% and 15% of melanoma cell lines, respectively, establishing MAPK signaling as a new therapeutic target in melanoma." (PMID 23340652, 2013). "BRAF and KRAS mutational analysis of lung adenocarcinoma, malignant melanoma and colorectal carcinoma by NGS LA: lung adenocarcinoma; MM: malignant melanoma; CRC: colorectal cancer." (PMID 23922754, 2013). "Of the three melanoma subtypes analyzed in considerable numbers (SSM, NM, ALM), percentages of BRAF and NRAS mutations combined were highest in SSM reaching 82%, lower in NM with 67% and lowest in ALM with 46%." (PMID 23694694, 2013). "Significantly, SAHA and the clinically available BRAF inhibitor vemurafenib cooperatively inhibited BRAFV600E melanoma xenograft growth in a mouse model even when caspase-3 was inhibited." (PMID 23744355, 2013). "IL-12 and TNF-α production by DCs exposed to supernatant from the BRAF mutant A375 melanoma cell line prior to maturation by LPS was suppressed." (PMID 24194739, 2013). "The exceptions seem to be under reporting of BRAF and KRAS mutations in melanomas and pancreatic cancers respectively (10% and 20% in this study vs. 43% and 58% respectively reported in COSMIC)." (PMID 23991070, 2013). "Instead, full length CSPG4 and BRAF-V600E both appear to be required for sustained Erk 1,2 activation and a CSPG4-specific mAb enhanced and increased the duration of the effects of a BRAF inhibitor in melanoma cells." (PMID 24069584, 2013). "Activating mutations in two of MAPK upstream regulators, BRAF and NRAS is seen in up to 80% of melanomas and also correlates with melanoma aggressiveness and poor prognosis." (PMID 23935925, 2013). "As previously observed, vemurafenib increased the mitochondrial content of melanoma cells sensitive to BRAF inhibitors." (PMID 24161908, 2013). "Melanomas arising in chronically sun-damaged skin, mucosal surfaces, and acral skin were characterized by wild-type BRAF and wild-type NRAS but exhibited alterations in KIT." (PMID 24416617, 2013). "As both MEK/BRAF inhibition and immune checkpoint blockade have recently taken center stage in the treatment of melanoma, a deeper understanding of how MAPK pathway inhibition affects the tumor immune response is needed." (PMID 24194739, 2013). "Further research needs to be conducted to evaluate the role of BRAF inhibitors in cancers other than melanoma." (PMID 23420786, 2013). "Conversely, BRAF inhibitors stimulate mitochondrial oxidative phosphorylation thereby promoting ROS production in melanoma cells." (PMID 24161908, 2013). "Here, we report that combinations of HDAC and BRAF inhibitors kill BRAFV600E melanoma cells by induction of necrosis." (PMID 23744355, 2013). "In 2002, researchers at the Sanger Institute (Cambridge, UK) discovered that mutations in the gene encoding the serine-threonine protein kinase rapidly accelerated fibrosarcoma isoform B (BRAF) occurred in >60% of melanomas initially tested." (PMID 23420786, 2013). "The aim of this study was to evaluate prevalence and distribution of pathogenetic mutations in BRAF and NRAS genes among melanoma patients with different geographical origin within the same Italian population." (PMID 23987572, 2013). "In summary, we have shown in this report that combinations of HDAC and BRAF inhibitors synergistically kill BRAFV600E melanoma cells by induction of necrosis." (PMID 23744355, 2013). "No activating mutations were detected in the kinase, juxtamembrane or extracellular domains the KIT gene, consistent with the observation that BRAF and KIT mutation are associated with different subsets of melanoma and are generally mutually exclusive." (PMID 24220097, 2013).